RNU6-138P (RNA, U6 small nuclear 138, pseudogene)
Gene: Small nuclear RNA gene on chromosome 3 (18,954,943 to 18,955,049, reverse strand). Ensembl gene ENSG00000251761.
Homologues: Orthologues: chimpanzee U6 (98% identical), macaque U6 (95% identical), guinea pig U6 (76% identical), pig U6 (71% identical), rabbit U6 (67% identical), rat LOC120097202 (65% identical), guinea pig U6 (62% identical), mouse Gm55985 (60% identical). Paralogues in human: RNU6-38P (78% identical), RNU6-224P (77% identical), RNU6-1145P (76% identical), RNU6-16P (76% identical), RNU6-468P (76% identical), RNU6-710P (76% identical), RNU6-883P (76% identical), RNU6-1083P (75% identical), RNU6-1084P (75% identical), RNU6-1131P (75% identical), RNU6-1227P (75% identical), RNU6-1316P (75% identical), and 1284 more.